RN7SL823P (RNA, 7SL, cytoplasmic 823, pseudogene)
Gene: Miscellaneous RNA gene on chromosome 19 (16,910,490 to 16,910,784, reverse strand). Ensembl gene ENSG00000263595.
Homologues: Orthologues: chimpanzee Metazoa_SRP (98% identical), macaque Metazoa_SRP (89% identical). Paralogues in human: RN7SL1 (84% identical), RN7SL2 (84% identical), RN7SL3 (83% identical), RN7SL408P (83% identical), RN7SL451P (81% identical), RN7SL679P (81% identical), RN7SL783P (81% identical), RN7SL113P (81% identical), RN7SL397P (81% identical), RN7SL492P (81% identical), RN7SL664P (81% identical), RN7SL743P (81% identical), and 703 more.